HNF4A (hepatocyte nuclear factor 4 alpha)
Diseases named in the same sentence as HNF4A in open-access papers (continued):
Sharing a sentence is not in itself a finding about the gene and the disease.
MODY (continued). "Reports of maternal treatment during pregnancy in HNF4A MODY are scarce." (PMID 28556992, 2017). "We have provided preliminary clinical proof-of-concept, and have mechanistically validated that the parallel measurements of serum PSP/reg1A and hsCRP levels in subjects with clinically suspected MODY may discriminate HNF1A-MODY from HNF4A-MODY." (PMID 23803251, 2013). "The answer is yes, as identifying MODY can guide management and more specifically, further subtyping of MODY based on genotypes can lead to individualized treatment such as the use of sulfonylureas in HNF1A and HNF4A mutations." (PMID 22936918, 2012). "Coding sequences of the genes causing MODY1-4 and MODY6 (GCK, HNF1A, IPF1, NEUROD1, and HNF4A) were sequenced in the proband to rule out known causes of MODY with compatible clinical presentations." (PMID 19216786, 2009). "The clinical features of the HNF4α phenotype as a subtype of MODY can overlap with type 1 diabetes." (PMID 20003313, 2009). "This biological function is shared by HNF4A, a known MODY gene." (PMID 19216786, 2009). "Even though we found no literature referring to the clinical significance of the HNF4A variant p.Y328C detected in patient 6, two variants in HNF4A located in adjacent amino acid residues (amino acids 326 and 327) have been associated with MODY." (PMID 39364395, 2024). "Therefore, GLP-1 receptor agonist (GLP-1 RA) could be an effective therapy to consider in HNF4A-MODY patients with sulfonylureas failure or requiring discontinuing insulin." (PMID 37711893, 2023). "Sanger sequencing for mutations in GCK, HNF1A, and HNF4A (the most common MODY genes) was negative." (PMID 34032641, 2021). "Although the GCK (MODY 2), HNF1A (MODY 3), and HNF4A (MODY 1) genes are responsible for the vast majority of genetic causes of MODY, there are other rarer MODY subtypes caused by mutations in genes not analyzed in this study, which could have been analyzed by next-generation sequencing methods." (PMID 31968686, 2020). "We consider this type of MODY the most difficult to distinguish from type 2 diabetes, since HNF4A-MODY patients at the diagnosis may be older and may present with dyslipidaemia similar to patients with type 2 diabetes, particularly higher LDL- and lower HDL-cholesterol." (PMID 30013516, 2018). "Patients with transcription factor-linked MODY have different associated features based on their underlying aetiology, such as glycosuria in HNF1A-MODY, fetal macrosomia and neonatal hypoglycaemia in HNF4A-MODY, and developmental disorders of the kidney and multiple other organs in HNF1B-MODY." (PMID 28314945, 2017). "However it is likely that many individuals with HNF4A-MODY remain undiagnosed." (PMID 23803251, 2013). "However, it is not known, whether they are dysregulated in diabetes type II or MODY and affect mRNAs such as HNF4A whose dysfunction leads to impaired insulin secretion." (PMID 22140441, 2011). "Best known for its implications as a monogenic, autosomal dominant form of maturity onset diabetes of the young (MODY), HNF4A is involved in development and function of both the liver and the pancreas and actively coordinates gene expression of many important metabolic pathways in both tissues." (PMID 20126273, 2010). "But Mutations in HNF4α (MODY1) are less frequent and may account for 2-5% of subjects with MODY." (PMID 20003313, 2009). "The most common MODY subtypes include GCK-(MODY2), HNF1A-(MODY3), HNF4A-(MODY3) and HNF1B-(MODY5), accounting for over 80% of all MODY cases." (PMID 40303944, 2025). "Strong genetic evidence confirms the etiological role of HNF1A, HNF4A, and GCK genes in the development of MODY." (PMID 39859454, 2025). "In this study we focused on the HNF1A, HNF4A and HNF1B genes (collectively referred to as HNF-MODY)." (PMID 40925988, 2025). "Targeted gene panel sequencing for 16 genes, including major forms of MODY (HNF1A-, HNF4A-, GCK- and HNF1B-MODY), was performed." (PMID 39717432, 2025).
MODY (continued). "This clinical response supported a presumptive diagnosis of MODY, likely the HNF1A or HNF4A subtype, although genetic confirmation is pending due to cost constraints." (PMID 40777711, 2025). "Of the 10 known MODY-associated TF genes, the three most common ones alone are estimated to account for more than two-thirds of all MODY cases: HNF1A (52%), HNF4A (10%), and HNF1B (6%)." (PMID 41356216, 2025). "This has changed the focus from only testing the most common MODY subtypes (HNF1A, HNF4A, and GCK) to testing for all subtypes." (PMID 40819284, 2025). "In Korean patients, the most common form of MODY was GCK gene lesions (50%), followed by HNF1A (21.4%) and HNF4A (21.4%) genes." (PMID 39902162, 2024). "Five out of eleven MODY genes were found affected, and these were GCK, HNF1B, HNF4A, PDX1, and RFX6." (PMID 39364395, 2024). "The most common forms of MODY in adults include GCK-MODY (30%–50%) and HNF1A-MODY (30%–50%) while HNF4A-MODY is much rarer (2%–5%)." (PMID 38933924, 2024). "The best‐known examples of precision medicine in MODY are seen in patients with HNF1A, HNF4A and GCK MODY." (PMID 35445424, 2022). "We excluded the possibility that these patients present the most common forms of MODY by sequencing GCK, HNF1A and HNF4A." (PMID 35625914, 2022). "Some MODY subtypes (e.g., ABCC8, KCNJ11, HNF1α, and HNF4α MODY) are manageable through KATP inhibition — i.e., sulfonylurea use." (PMID 34032641, 2021). "However, most of the HNF4A mutations do not demonstrate a dominant-negative effect on the gene expression profiles, and it is still not clear how moderate decreases in HNF4A activity cause disease in MODY patients." (PMID 34299172, 2021). "Mutations in the hepatocyte nuclear factor 1-alpha (HNF1A), glucokinase (GCK), hepatocyte nuclear factor 4-alpha (HNF4A), and hepatocyte nuclear factor 1-beta (HNF1B) genes are the most frequently identified aetiologies of MODY." (PMID 34496959, 2021). "A genetic screening study among the Chinese population included 74 clinically highly suspected MODY patients from 59 unrelated families with a detection rate in HNF1A and HNF4A of 13.6% and 1.7%, respectively." (PMID 34421822, 2021). "For example, most laboratories will first screen HNF1A, followed by HNF4A and GCK in subjects exhibiting the classical features of MODY; and first GCK, then HNF1A and HNF4A, if the diabetic phenotype is mild and fasting glucose 5.5–8.5 mmol/l." (PMID 22662265, 2012). "The sulfonylurea trial was empiric, based on the clinical presentation, history, and laboratory results, as genetic subtype confirmation of MODY (e.g., HNF1A or HNF4A mutations) was not available." (PMID 41306149, 2025). "GCK, HNF4A and HNF1A are the most common types of MODY in China." (PMID 40303944, 2025). "Studies have shown that de novo mutations in common MODY genes such as HNF1A, HNF4A, and GCK occur in approximately 7% of MODY cases without a family history, underscoring the importance of considering MODY even in the absence of familial diabetes." (PMID 41020216, 2025). "Similarly, in Norway, HNF1A accounted for 53% of MODY cases, GCK for 30%, HNF4A for 7.5%, and HNF1B for 5.6%." (PMID 41153735, 2025). "The impact of maternal glycaemic control on birth weight and neonatal hypoglycaemia in HNF4A-MODY is not described in the literature." (PMID 38933924, 2024). "In our cohort, the prevalence of pathogenic variants on these genes were respectively, 0.006%, 0.080%, and 0.006%, which demonstrated a higher prevalence for GCK-MODY, and lower for HNF1A-MODY and HNF4A-MODY comparing to other cohorts, including UK biobank and Geisinger cohort." (PMID 39191897, 2024). "HNF4A MODY (previously MODY1) is diagnosed less commonly, accounting for 5–10% of all MODY cases." (PMID 39408828, 2024). "Such are the cases of heterozygous mutations in the genes ABCC8, HNF1B, HNF4A, HNF1A, GATA4, and GATA6 that cause neonatal diabetes or MODY in humans, but do not present any diabetic pathophysiology in mice." (PMID 33692757, 2021).
MODY (continued). "In 46 families with clinically suspected MODY, mutations were found in 23 (50%) families, including seven GCK, HNF1A, and HNF4A mutations that have not previously been reported." (PMID 31968686, 2020). "Additional MODY genes are HNF1A and HNF1B, which functionally interact with HNF4A, thereby defining a transcriptional network responsible for phenotypically indistinguishable forms of MODY." (PMID 31875549, 2019). "Individuals from the UK with GCK- or HNF1A/HNF4A-MODY who were not on recommended treatment at the time of genetic diagnosis, and who were diagnosed below the age of 30 years and were currently aged less than 50 years, were eligible to participate." (PMID 30229274, 2018). "To identify patients with novel heterozygous PTVs, we first assessed 38 European (non-Finnish) probands with a strong MODY-like phenotype who did not have mutations in the common MODY genes (GCK, HNF1A, HNF4A) by Sanger sequencing." (PMID 29026101, 2017). "The standard approach for diagnosis of MODY includes sequential screening of the first three common MODY genes which include hepatocyte nuclear factor 1alpha (HNF1A), hepatocyte nuclear factor 4 alpha (HNF4A) and Glucokinase (GCK)." (PMID 28095440, 2017). "MODY and RCAD are autosomal dominant disorders, thought to be mediated by a haploinsufficiency-based mechanism due to a reduced amount of HNF-1α, HNF-1β or HNF-4α proteins." (PMID 19924231, 2009). "HNF4A-MODY constitutes 5%–10% of MODY cases; however, treatment options remain unclearly recommended, and long-term follow-up of patients with HNF4A-MODY is lacking due to limited research." (PMID 40589512, 2025). "In a recent study, among 16 patients with MODY who were offered treatment switch after genetic diagnosis, nine (six HNF1A, three KCNJ11) were stably switched from insulin to oral sulfonylurea but seven (three HNF4A, two ABCC8 and one each HNF1A and KCNJ11) had to restart insulin." (PMID 35618782, 2022). "Seven variants (GCK c.494T>C, GCK c.563C>G, HNF1A c.1623G>A, HNF1A c.1729C>G, HNF4A c.68delG, HNF4A c.422G>C, HNF4A c.602A>C) have not previously been reported in patients with MODY and were found to be absent or very rare (≤0.0001) in the gnomAD population database." (PMID 31968686, 2020). "This may be more pronounced in islet-cells, where Hnf1α and Hnf4α concentrations are much lower than in liver and other tissues that are not clinically afflicted in MODY." (PMID 20523905, 2010). "Secondly, since MODY is known to be a disorder of haploinsufficiency, we cannot rule out the possibility that there may also be species-specific differences in the dosage of the HNF1A, HNF1B and HNF4A gene products that are required for full function." (PMID 19924231, 2009). "GCK-MODY leads to stable and mild fasting hyperglycemia due to reduced glucokinase enzyme activity and typically does not require pharmacologic treatment, whereas HNF1A-MODY and HNF4A-MODY are associated with progressive β-cell dysfunction and are often highly responsive to sulfonylurea therapy." (PMID 41367630, 2025). "A correct genetic diagnosis of MODY may alter the therapeutic approach: patients with glucokinase (GCK) MODY usually do not require pharmacological treatment, and those with either hepatocyte nuclear factor 4-α (HNF4A) or hepatocyte nuclear factor 4-α (HNF1A) MODY are very sensitive to sulfonylurea." (PMID 32411229, 2020). "Recent study has revealed much higher frequency of spontaneous de-novo mutations in GCK, HNF1A and HNF4A genes than previously assumed; moreover in GCK-MODY, discrete fasting hyperglycaemia may not be yet recognized in a parent, thus, family history could be seemingly negative." (PMID 30013516, 2018). "GCK-MODY typically does not require drug therapy, whereas other forms of MODY, such as HNF1A, HNF4A, and KCNJ11, generally respond well to sulfonylurea therapy." (PMID 40149950, 2025).
MODY (continued). "It is well established that patients affected by GCK-MODY do not require any pharmacological treatment, while patients with HNF1A or HNF4A-MODY have a good response to sulfonylureas in term of glycaemic control and prevention of micro- and macrovascular complications." (PMID 34496959, 2021).
hepatocellular carcinoma (131 papers, 2006 to 2026). A malignant tumor that arises from hepatocytes. "In colorectal and hepatocellular carcinoma, reduced HNF4α activity accompanies loss of differentiation and tumor progression, consistent with tumor-suppressive functions." (PMID 41925866, 2026). "The HNF4α/miR-122 axis comes into play in HBV-associated HCC as well, where a ChIP assay showed a decreased association of HNF4α with miR-122 promoter in HBV-infected hepatoma cells." (PMID 34771521, 2021). "For example, it is known that hepatocellular carcinoma (HCC) progression is associated with downregulation of HNF-4α and glycogen metabolism has an important role for cancer cell survival." (PMID 34622807, 2021). "Considering that the suppression of HNF4α was associated with the ERK signaling pathway in human hepatoma cell lines, we then investigated the level of activated ERK in mice tissues." (PMID 32023898, 2020). "The resulting disruption of the HNF-4α/HNF-1α pathway is also linked to hepatocellular carcinoma metastasis and enhanced apoptosis in pancreatic cancer cells." (PMID 33371430, 2020). "Decreased PGC-1α is also associated with dedifferentiation of human hepatoma cell lines through impairment of hepatocyte nuclear factor 4 alpha (HNF4α), a transcription factor critical for liver development." (PMID 31623280, 2019). "One of the key events during the progression of hepatocellular carcinoma is the loss of expression of master genes of epithelial/hepatocyte differentiation, such as HNF4α and HNF1α, that play a pivotal role in the restraint of inflammation, fibrosis, and EMT." (PMID 31543815, 2019). "In humans, changes in HNF4A expression were associated with liver, colon, and hepatocellular carcinoma tumorigenesis." (PMID 31426508, 2019). "Low HNF4-α expression has been associated with worst prognosis of hepatocellular carcinoma (HCC) through a robust activation of RELA, whereas higher HNF4-α expression inhibited NF-κB expression and improved HCC outcome." (PMID 27192147, 2016). "Depletion of HNF4α in HCV infection-associated hepatocellular carcinoma promotes EMT genes and tumor progression." (PMID 26157476, 2015). "Previous evidence shows that HNF4α expression is diminished in hepatocellular carcinoma, and loss of HNF4α leads to increased hepatocyte proliferation and promotion of diethylnitrosamine-induced hepatic tumors secondary to aberrant c-Myc activation." (PMID 25965823, 2015). "Aberrant and altered changes in HNF4α have been associated with the development of several cancer types, including hepatocellular carcinoma (HCC), renal cell carcinoma (RCC), pancreatic adenocarcinoma (PAAD), stomach adenocarcinoma (STAD), cholangiocarcinoma, and colorectal adenocarcinoma (CRAC)." (PMID 40277924, 2025). "The role of HNF4A in the cellular identity of hepatocytes is interesting: P1-HNF4A acts as a tumor suppressor, whereas increased expression of P2-HNF4A is associated with the progression of hepatocellular carcinoma." (PMID 41511298, 2025). "Similarly, in hepatocellular carcinoma, we have previously shown that HNF4A loss is an early event that drives hepatocellular transformation, and this suppression becomes a stable event through an epigenetic switch." (PMID 39165427, 2024). "Moreover, we discover a signaling axis in which liver-TEs, KDM1A, and the liver-TE-associated gene (HNF4A) synergistically control the proliferation of hepatocellular carcinoma cells." (PMID 38965210, 2024). "These cells express the CCA markers SRY (Sex Determining Region Y)-Box 9 (SOX9), cytokeratin (CK)-7 and 19 but lack hepatocyte nuclear factor 4 alpha and alpha-smooth muscle actin, markers of hepatocellular carcinoma and cancer-associated fibroblasts, respectively." (PMID 29464042, 2018).
hepatocellular carcinoma (continued). "Aberrations in HNF4α functionality are linked to development of severe cirrhotic livers, alcoholic liver disease, tumor necrosis factor-α-induced hepatotoxicity, and hepatocellular carcinoma where HNF4α has antiproliferative effect and serves as a tumor suppressor." (PMID 24427299, 2014). "Hnf4a is essential to liver development and maintenance, and when suppressed, it can cause epigenetic changes that lead to increased incidence of hepatocellular cancer [59 Reduced expression of miR-449 in aging liver would increase Hnf4a expression, possibly preventing hepatocyte transformation." (PMID 23852002, 2013). "Thus, we demonstrate cyclosporine treatment of human hepatoma cells to significantly reduce DNA-binding of HNF4α to AGT and AGTR1 at gene specific promoters to cause impaired gene expression." (PMID 21298017, 2011). "Furthermore, HNF4α impairment is implicated in the development of organ fibrosis (i.e., liver and renal fibrosis) and in the onset of various cancers, including hepatocellular carcinoma, renal cell carcinoma, and pancreatic ductal adenocarcinoma." (PMID 41595461, 2025). "Numerous studies have reported that the expression of HNF4α is dysregulated in hepatocellular carcinoma (HCC) and associated with the development and progression of HCC, thus providing new insight into HCC tumorigenesis." (PMID 33462379, 2021). "Irregular expression or mutations in the HNF-4α gene promote or prevent definitive endoderm differentiation, cause monogenic autosomal dominant non-insulin-dependent diabetes mellitus type I, and possibly contribute to the progression of hepatocellular carcinoma." (PMID 33371430, 2020). "Hepatocyte nuclear factor-4α (Hnf4α), known as the master regulator of hepatocyte differentiation, was also demonstrated to be closely linked to hepatocarcinogenesis since an extensive microarray analysis on Hnf4a−/− mice suggested that its loss may directly contribute to hepatocellular carcinoma." (PMID 25826080, 2016). "Gene perturbation analysis revealed that TMEM64 expression is increased upon hepatocyte nuclear factor 4 alpha (HNF4α) depletion in HepG2 hepatocellular carcinoma cells." (PMID 41472678, 2025). "In various conditions such as high-fat diet (HFD)-fed mice, db/db mice, and palmitate-treated hepatoma cells, acetylation modification of HNF4α increases, leading to its protein degradation." (PMID 38346961, 2024). "Further analysis of RNA-seq data in hepatocellular carcinoma with KDM1A downregulation revealed significant enrichment of conserved motifs of HNF4A in the promoters of KDM1A-negative regulatory genes (HOMER: P = 1e−14, Rank 1)." (PMID 38965210, 2024). "Similarly, ectopic HNF4α expression in hepatocellular carcinoma (HCC) is associated with increased miR-122 expression, which induces re-differentiation, mesenchymal-to-epithelial transition, and decreased invasive capacity." (PMID 37974020, 2023). "Western blot analyses performed using lysates from hepatoma cells treated with IL-1ß confirmed reduced HNF4α expression upon IL-1ß treatment." (PMID 37175814, 2023). "Hepatocyte nuclear factor 4 A (HNF4A), an orphan nuclear receptor, was one of the most important regulators of hepatocyte homeostasis, whose expression was frequently decreased in hepatocellular carcinoma." (PMID 36866237, 2023). "On the other hand, circRNA_104075 can regulate HNF4A to further stimulate YAP-dependent tumorigenesis in hepatocellular carcinoma." (PMID 38057879, 2023). "The expression of downstream genes of HNF4α was suppressed by reduced nuclear localization of HNF4α in human hepatoma cells." (PMID 35800776, 2022). "Correlation coefficient analysis between expression of the HNF4a and top 50 epithelial and mesenchymal genes across liver carcinoma samples was performed." (PMID 36132168, 2022). "The scatter plot depicts positive association between HNF4a and the expression levels of ZO1 and ALB across 372 liver carcinoma samples from TCGA." (PMID 36132168, 2022).